TNF (tumor necrosis factor)
Diseases named in the same sentence as TNF in open-access papers (continued):
Sharing a sentence is not in itself a finding about the gene and the disease.
CADASIL (2 papers, 2023 to 2025). "Our findings suggest that the inflammatory pathway, particularly the TNF-related inflammatory pathway, may be involved in the disease progression of CADASIL." (PMID 41000387, 2025). "The TNF-related inflammatory pathway may be a promising therapeutic target for CADASIL." (PMID 41000387, 2025). "Previous studies have detected systemic inflammatory cytokines, including IL-1β, IL-6, TNF-α, CCL2, and CXCL16, and found that their expression levels were significantly elevated in CADASIL patients, which is consistent with our results." (PMID 41000387, 2025). "The serum inflammatory cytokines were analyzed by ELISAs and revealed that the levels of serum IL-1β, IL-6, TNF-α, CCL2, and CXCL16 were significantly elevated in the patient group compared with their family members, suggesting a systemic inflammation in CADASIL patients." (PMID 37684694, 2023).
Can (2 papers, 2022 to 2024). "Additionally, TNFα is increased in patients with acute allograft rejection and chronic allograft nephropathy." (PMID 35806457, 2022). "In natural Can-VL infection, the protective cellular immunity is related to increase in Th1 mediated by IFN-γ and TNF-α." (PMID 38399674, 2024).
cardiac interstitial fibrosis (2 papers, 2018 to 2022). "Additionally, cardiac interstitial fibrosis was not affected by neutrophil depletion, whereas Gr-1+ cells other than neutrophils increased cardiac fibrosis at day 21 p.i. by increasing cardiac expression of profibrotic cytokine TNF-α and TGF-β." (PMID 29868513, 2018).
central nervous system infection (2 papers, 2017 to 2021). "Pharmacotherapies designed to suppress TNFR1-mediated or augment TNFR2-mediated effects of TNFα may provide antiseizure and disease-modifying effects after central nervous system infection." (PMID 28497109, 2017). "However, TNF-α deficiency did not affect the brain bacterial titers and leukocyte recruitment into the subarachnoid space in the mouse model of central nervous system infection in one study." (PMID 34437417, 2021).
Cerebellar atrophy (2 papers, 2011 to 2025). Cerebellar atrophy is defined as a cerebellum with initially normal structures, in a posterior fossa with normal size, which displays enlarged fissures (interfolial spaces) in comparison to the foliae secondary to loss of tissue. "These overactive microglia can produce highly neurotoxic factors, including superoxide, TNF-α, and IL-1β, which are likely to perpetuate neuronal death and lead to overt cerebellar atrophy in iPLA2β-/- mice." (PMID 22046428, 2011). "Moreover, glial cell activation and the elevation in TNF-α and IL-1β expression occurred before apparent cerebellar atrophy." (PMID 22046428, 2011).
cerebral artery occlusion (2 papers, 2015 to 2022). "OPG has been shown to be upregulated by ischemia in juvenile rats and mice and in a murine model of middle-cerebral artery occlusion, OPG deletion results in decreased infarct volume, reduced brain edema, downregulation of IL-6 and TNF-α, and diminished infiltration of macrophages." (PMID 36403069, 2022).
Cerebral atrophy (2 papers, 2023 to 2025). Atrophy (wasting, decrease in size of cells or tissue) affecting the cerebrum. "Two studies reported associations between circulating TNFα and increased cerebral atrophy, particularly in MAPT-FTD patients, but not in those with C9ORF72- or GRN-mediated FTD." (PMID 40305176, 2025).
cervical squamous cell carcinoma (2 papers, 2017 to 2022). A squamous cell carcinoma arising from the cervical epithelium. "MLKL was initially identified as a key mediator of TNF-induced necroptosis and can be used to assess the prognosis of patients with cervical squamous cell carcinoma, and TNF is also important for immune and cellular homeostasis in mammals." (PMID 36685937, 2022). "Notably, tumour necrosis factor (TNF)-α induced KLF5 expression by activating the p38 signalling pathway and high KLF5 and TNFRSF11a expression increased the risk of death in patients with cervical squamous cell carcinoma." (PMID 29146991, 2017). "MLKL is a prognostic biomarker for cervical squamous cell carcinoma and has recently been identified as a key RIPK3 downstream component of TNF-induced necroptosis." (PMID 36685937, 2022).
chilblain lupus (2 papers, 2014 to 2025). "To date, there are only 11 published cases of chilblain lupus as a presentation of anti-TNF-α-induced lupus." (PMID 40160999, 2025). "A diagnosis of TNF-α inhibitor–induced chilblain lupus was made." (PMID 40160999, 2025). "There have even been cases of tumor necrosis factor inhibitor-induced lupus chilblains." (PMID 25416648, 2014).
chronic kidney failure (2 papers, 2023 to 2024). "In an in vivo study involving uremic rats with chronic kidney failure, it was observed that rats fed a diet containing 0.1% Mg experienced increased pro-inflammatory cytokines like TNF-α, IL-1β, and IL-6, resulting in the induction of oxidative stress." (PMID 39200118, 2024).
chronic myelomonocytic leukaemia (2 papers, 2021 to 2024). "Bryostatin-1 induced proinflammatory cytokines such as IL-8, IL-1β, TNF-α, and IL-6 in human monocytes and increased TNF-α secretion of chronic myelomonocytic leukemia cells." (PMID 39877358, 2024).
chronic skin ulcers (2 papers, 2010 to 2024). "It has been shown that persistently elevated TNF-α levels in patients with chronic skin ulcers may impair healing and that treatment with infliximab may reverse this process rapidly." (PMID 20659338, 2010).
Clostridium infection (2 papers, 2022 to 2024). "As TNF-α levels rise during a Clostridium infection, TNF-α related inflammation and hemodynamic instability would also be expected to increase." (PMID 35300484, 2022).
compartment syndrome (2 papers, 2016 to 2024). Elevated pressure in a confined space enclosed by fascia or eschar, which may lead to vascular compromise and subsequent ischemic injury to the tissue within the space. "Ischemia and subsequent reperfusion increase polymorphonuclear leukocytes, tumor necrosis factor, leukotrienes, and free oxygen radicals, which cause fluid leakage from the intravascular compartment and the clinical table of compartment syndrome." (PMID 26885421, 2016).
Corneal opacity (2 papers, 2009 to 2022). A reduction of corneal clarity. "Lornoxicam treatment significantly decreased the incidence of recurrent HSK, attenuated the corneal opacity scores, and also effectively suppressed both NF-κB activation and TNF-α expression in biological analysis." (PMID 19547717, 2009). "The use of the TNF-α antibody can effectively reduce the degree of HSK corneal opacity." (PMID 35992663, 2022).
delayed hypersensitivity reactions (2 papers, 2022 to 2024). "Metal implants have the potential to trigger a type IV hypersensitivity reaction, where macrophage activation, induced by implant debris, leads to the release of interleukin (IL)-1b, the tumor necrosis factor, IL-6, and IL-8." (PMID 38592148, 2024). "There is good evidence from the murine passive cutaneous anaphylaxis model and delayed hypersensitivity reactions in skin, that leukocyte recruitment is dependent on MC-derived TNFα, and that CD8+ dendritic cell migration to draining lymph nodes of the skin also relies on MC TNFα." (PMID 35967445, 2022).
denture stomatitis (2 papers, 2015 to 2020). Inflammation of the mouth due to denture irritation. "We have recently demonstrated that higher TNFα production and inflammation in oral mucosa was associated with C. albicans infection in denture stomatitis." (PMID 26146640, 2015). "We have also shown that denture stomatitis involving C. albicans is associated with higher levels of TNFα in fluids from the oral palatal mucosa." (PMID 26146640, 2015).
developmental delay (2 papers, 2020 to 2025). "Elevated cord blood levels of tumor necrosis factor (TNF) are strongly associated with impaired neuronal activity in the first few days of life and developmental delay at 2 years of age." (PMID 32293473, 2020).
dissection (2 papers, 2015 to 2024). The separation and isolation of tissues for surgical purposes, or for the analysis or study of their structures. "In comparison to the control group, the aortic dissection model group exhibited decreased expression of MMP-2 and NF-κB in PVAT, while TNF-α and RUNX1 expression increased." (PMID 38693222, 2024).
Dry skin (2 papers, 2020 to 2021). Skin characterized by the lack of natural or normal moisture. "Furthermore, due to the dysfunction of EGFR, the release of cytokines such as IL-6 and TNF-α and the decreased production of cell adhesion factors such as claudin resulted in dry skin." (PMID 32252690, 2020).
egg allergy (2 papers, 2016 to 2023). A food allergy that is an allergy or hypersensitivity to dietary substances from the yolk or whites of eggs, causing an overreaction of the immune system which may lead to severe physical symptoms. "On the other hand, no negative nor positive association was found between IL-10, IFN- γ and TNF-α responses at 4 months of age in children with IgE-mediated hen’s egg allergy at age 12 months." (PMID 36756279, 2023). "Using a combination of differential gene expression and multiplex cytokine measurement, we observed that egg allergy was associated with IL-9, IL-5, and TNFα expression and secretion, as well as expression of CEACAM1, and CISH." (PMID 27788149, 2016). "Following LPS stimulation, IL-6 and IL-1β production was more elevated in both persistent and transient hen’s egg allergy in comparison to healthy controls at follow-up but increased production of TNF-α and IL-8 was unique to infants with persistent hen’s egg allergy." (PMID 36756279, 2023).
encephalitozoonosis (2 papers, 2017 to 2020). Infection with fungi of the genus encephalitozoon. "The present results showed an increase of TNF-α in DM-Infected mice, however this cytokine is not the most effective against encephalitozoonosis." (PMID 29091912, 2017).
endometrial adenocarcinoma (2 papers, 2008 to 2018). "In endometrial adenocarcinoma, expression levels of the downstream molecules TNFα and NF-κB were decreased in G2 and G3 but not in the well-differentiated grade 1 carcinoma." (PMID 18775079, 2008).
endometrioid ovarian cancer (2 papers, 2023 to 2025). "Inflammatory mediators and cytokines, including tumor necrosis factor-alpha (TNF-α), interleukin 6, and interleukin 1β, influence the development, expansion, and advancement of endometrioid ovarian cancer." (PMID 41415877, 2025).
eosinophilic disease (2 papers, 2012 to 2026). "Indeed, eosinophilic diseases have been associated with TNFα, IL-5, IL-10, and eotaxin-3, while IL-10 was overexpressed in IgG4RD." (PMID 22333532, 2012). "Following anti-TNF withdrawal, eosinophilic disease persisted, prompting compassionate off-label treatment with benralizumab, an interleukin-5 (IL-5) receptor α-antagonist, alongside vedolizumab for CD maintenance." (PMID 42110122, 2026).
eosinophilic gastrointestinal disease (2 papers, 2021 to 2026). "This case illustrates persistent anti-TNF-associated immune deviation and supports targeted IL-5 receptor blockade as an effective strategy for refractory eosinophilic gastrointestinal disease while maintaining CD remission." (PMID 42110122, 2026).
eosinophilic pneumonia (2 papers, 2020 to 2021). An inflammatory lung disorder characterized by an increased number of eosinophils in the lungs. "The main mechanism of acute eosinophilic pneumonia has been elucidated to be due to pro-inflammatory cytokines such as IL-5, IL-6, IL-7, and tumor necrosis factor." (PMID 32366239, 2020).
epididymitis (2 papers, 2023 to 2025). Inflammation of the epididymis. "The LPS-induced mouse epididymitis model was validated by significantly increased expression of IL-6 and TNF-α in both the caput and cauda epididymis at 72 hours post-injection." (PMID 41445755, 2025). "In the vivo experiments, levels of the proinflammatory cytokines IL-1α, IL-6, IL-17A, TNF-α, IL-1β, MCP-1, and GM-CSF, mRNA for MyD88 related genes, and the percentages of monocyte-derived DCs (Mo-DCs) were significantly elevated in mice with epididymitis." (PMID 37175545, 2023).
erythema multiforme (2 papers, 2021 to 2022). Erythema multiforme (EM) refers to a group ofhypersensitivity disorders characterized by symmetric red, patchy lesions, primarily on the arms and legs. "Predominance of CD4+ T-lymphocytes and IFN-γ was shown in herpes associated erythema multiforme (HAEM), while in a drug-induced erythema multiforme (DIEM) there is involvement of monocytes, CD8+ T-lymphocytes and tumor necrosis factor-α (TNFα)." (PMID 33916862, 2021). "On the other hand, TNF-α, which is mainly produced by monocytes rather than activated T-cells, was shown to be a major cytokine in drug induced erythema multiforme (DIEM)." (PMID 33916862, 2021).
erythroleukemia (2 papers, 2017 to 2022). Acute erythroid leukemia characterised by the presence of at least 50% erythroid precursors and at least 20% myeloblasts in the bone marrow. "Upon coculture with K562 cells, an erythroleukemia cell line that lacks HLA-I expression, ITNKs were induced to secrete proinflammatory cytokines, including GM-CSF, IFN-γ and TNF-α, and lyse K562 cells." (PMID 35331335, 2022). "In vitro studies were carried out in K562 cells (human erythroleukemia cell line) in the presence/absence of TNF-α." (PMID 28303002, 2017).
febrile convulsions (2 papers, 2022 to 2024). "Another clinical study demonstrated that febrile convulsions increase the levels of cytokines IL-1β, IL-6, and TNF-α in cerebrospinal fluid." (PMID 39315097, 2024).
femoral neck fracture (2 papers, 2015 to 2022). Fractures of the short, constricted portion of the thigh bone between the femur head and the trochanters. "Hip chondrocytes from patients with OA or femoral neck fracture (non-OA) were stimulated with IL-1β, TNF, forskolin and opioid peptides." (PMID 35740371, 2022).
fertility disorders (2 papers, 2012 to 2021). "Other studies have indicated that the overproduction of TNF-alpha may be associated with fertility disorders, as well as miscarriages or recurrent implantation failure syndrome." (PMID 34573352, 2021). "At the same time, TNF-α is a kind of cell factor, which has close relations with sterility occurrence and development." (PMID 23209346, 2012). "In conclusion, low expression of PAF or high expression of TNF-α in leukocytospermia affects the sperm quality, both of which contributed to sterility." (PMID 23209346, 2012).
Fibroadenoma (2 papers, 2024). A benign tumor of the breast characterized by the presence of stromal and epithelial elements. "In the HER2(−) group, compared to the control and fibroadenomas, the highest level was shown for cytokines TNF-α (2.65 pg/mL) and IL-18 (67.05 pg/mL)." (PMID 39456554, 2024).
fluorosis (2 papers, 2024). "In addition, various inflammatory indicators (TNF-α, IL-1β, NF-κB), and other fluorosis-related indicators (Mag, GSK3β) were also included to assess spinal cord injury in fluorosis rats." (PMID 39687171, 2024). "Whether inflammatory factors such as SDF-1/CXCR4, IL-6, TNF-α, NF-κB, and IL-1β play a role in the hepatic system due to fluorosis deserves further exploration." (PMID 38905184, 2024). "Therefore, the present study aimed to further investigate the role of the CXCL12/CXCR4 signaling axis and the related inflammatory factors IL-1β, TNF-α, IL-6 and NF-κB in the mechanism of fluorosis-induced liver injury at the cellular level." (PMID 38905184, 2024).
focal epilepsy (2 papers, 2023 to 2024). A seizure caused by a localized disorder. "Previous studies have suggested a significant increase in TNF-α in focal epilepsy, and our MR study supports this." (PMID 39259090, 2024). "Specifically, focal epilepsy onset may induce increases in cytokines such as IL-7, IL-1Ra, IL-10, TNF-α, IFN-γ, and IL-1β, whereas inconsistent cytokine levels, including IL-5 and IL-1ra, may influence variations in focal epilepsy risk." (PMID 39259090, 2024).
follicular thyroid cancer (2 papers, 2016 to 2021). "In addition to high levels of osteopontin, p-AKT and integrin β1, TGFβ and tumor necrosis factor-alpha (TNFα) exhibited an outstanding expression in follicular thyroid cancer." (PMID 34680488, 2021).
ganglionitis (2 papers, 2015 to 2024). "Similarly, and despite being implicated in the damage to enteric neurons in a model of ganglionitis, TNF was not required for intestinal motility defects in WNV-infected mice." (PMID 39207863, 2024).
gastrointestinal lymphoma (2 papers, 2021 to 2024). A non-Hodgkin or Hodgkin lymphoma that arises from any part of the digestive system, with the bulk of the disease localized to that site. "Previous studies have shown that long-term immunosuppressive drugs and tumor necrosis factor (TNF) inhibitor therapy in patients with UC induce gastrointestinal lymphoma." (PMID 33478454, 2021).
generalized epilepsy (2 papers, 2022 to 2025). Epilepsy that is characterized by generalized seizure types and may have typical interictal and/or ictal EEG findings that accompany generalized seizure types (for example generalized spike-wave). "A clinical study of 21 generalized epilepsy patients revealed that VPA treatment for 4–6 months decreased the serum level of IL-6 but not that of IL-1β or TNF-α." (PMID 40806813, 2025). "The aim of this study was the investigation of TNF-α, IL-10, IL-6, and IL-1β cytokines secretion in PBMC supernatants isolated from children affected by generalized epilepsy and treated in vitro with myofibrillar, sarcoplasmic, and total protein fractions of meat and fish sources." (PMID 35684043, 2022).
generalized tonic-clonic seizures (2 papers, 2014 to 2024). "The effect of sertraline at doses within the range of 0.75 to 25 mg/kg on the increase in IL-1β and TNF-α mRNA expression accompanying generalized tonic-clonic seizures, and increase in the pro-inflammatory cytokines expression induced by lipopolysaccharide was also investigated." (PMID 25364907, 2014).
Gingival bleeding (2 papers, 2018 to 2021). Hemorrhage affecting the gingiva. "Compared to the low gingival bleeding group, the levels of IL-1β in the high gingival bleeding group were significantly higher, and the levels of TNF-α were significantly lower in the high gingival bleeding group." (PMID 34199256, 2021).
granuloma annulare (2 papers, 2019 to 2024). Granuloma annulare is a long-term (chronic) skin disease consisting of a rash with reddish bumps arranged in a circle or ring. "The role of TNF-α producing macrophages in granuloma formation points to a key role of this cytokine in granuloma annulare." (PMID 31440261, 2019). "A summary of published cases showed that 20/26 patients with granuloma annulare responded to anti-TNF-α treatment." (PMID 31440261, 2019). "Overall, these data support a high efficacy of TNF-α inhibitors in granuloma annulare although well-designed RCTs are missing." (PMID 31440261, 2019).
Hematuria (2 papers, 2018 to 2021). The presence of blood in the urine. "NKT cells injured kidney vascular endothelial cells by perforin-mediated pathway and tubular epithelial cells by tumor necrosis factor (TNF)-α/FasL pathway, leading to AKI with hematuria in mice." (PMID 34616308, 2021). "NKT cells injured kidney vascular endothelial cells by perforin-mediated pathway and tubular epithelial cells by TNF-α/FasL pathway, leading to AKI with hematuria in mice." (PMID 34616308, 2021).